TIMP1 (TIMP metallopeptidase inhibitor 1)
Diseases named in the same sentence as TIMP1 in open-access papers (continued):
Sharing a sentence is not in itself a finding about the gene and the disease.
glioma (continued). "The PDPN and TIMP1 may serve as potential biomarkers for prognosis of glioma." (PMID 33123464, 2020). "Moreover, researchers have shown that both serum TIMP1 level and TIMP1 mRNA expression of glioma tissue in GBM patients were significantly higher than grade II/III patients, and serum angiogenic profile in GBM patients identified that the serum TIMP-1 level as an independent predictor of survival." (PMID 32547876, 2020). "In addition, PDPN and TIMP1 were found to be highly expressed in high-grade glioma via The Human Protein Atlas database, and both correlated with m6A and macrophage marker CD68 in glioma tissue samples, which may serve as potential biomarkers for glioma prognosis." (PMID 38071304, 2023). "The top 20 network analysis indicated that PTX3, TIMP1, CHI3L1, LTF and IGFBP3 comprise a crucial role in gliomas progression." (PMID 36153549, 2022). "Next, glioma scRNA-seq datasets (GSE84465 40 and GSE148842 41) were analyzed to validate the relationship between TGFBI, TIMP1 and M2-like TAMs." (PMID 35673564, 2022). "Our study firstly established a seven-gene signature comprising METTL3, COL18A1, NASP, PHLPP2, TIMP1, U2AF2, and VEGFA with a good capability for predicting survival in glioma." (PMID 34589481, 2021). "TIMP1 has been suggested to interact with P75NTR in metastatic carcinoma and glioma cells, and silence of TIMP1 or inhibition of NF-kappa B activity led to slower tumor growth in vivo." (PMID 33123464, 2020). "And as illustrated in the box plots, IGFBP2, EMP3, TIMP1 and SERPINE1 were all highly expressed in glioma tumor tissues, compared with the normal brain tissues." (PMID 32328202, 2020). "The prognostic significance of age related genes IGFBP2, EMP3, TIMP1 and SERPINE1 were further demonstrated in Kaplan-Meier survival analysis in glioma patients." (PMID 32328202, 2020). "Increased levels of MMP-2 and 9 were observed in CSF of high-grade glioma patients, and a larger study confirmed increased plasma levels of MMP-9 and TIMP-1 in patients with both grade II and IV glioma compared to healthy controls." (PMID 25720744, 2015). "Additionally, glioma cluster 2 cells expressed selectins (LGALS1 and LGALS3), integrins (ITGB1), and glycosylation targets (VIM, TIMP1, HIF1A, and CD44)." (PMID 39333557, 2024). "In metastatic carcinoma and glioma cells, TIMP1 has been demonstrated to interact with P75NTR, TIMP-1, and CD63, and may play a role in glioblastoma stemness." (PMID 37091145, 2023). "There is clear evidence that PTX3, TIMP1, and TUBA1C are related to glioma invasion." (PMID 37091145, 2023). "High GNAI, EMP3, TIMP1, ITGA5, and NMI while low PCDH7, CALCRL, and NFKBIA expressions could lead to poor prognoses in glioma patients." (PMID 35647198, 2022). "Other indicators of EMT activation in glioma NS include MMP1, TIMP1 and PLOD2." (PMID 36231068, 2022). "In addition, the local administration of THC down-regulated TIMP-1 and MMP-2 expression in glioma-bearing mice and in two patients with recurrent GBM." (PMID 35454080, 2022). "Interestingly, THC treatment depressed TIMP-1 and MMP-2 expression in glioma cell lines as well as in cultured human GBM primary cells." (PMID 35454080, 2022). "In addition, the levels of the tissue inhibitors of metalloproteinases (TIMP)-1 and TIMP-2 decreased after FABP6 reduction in glioma cells." (PMID 34685761, 2021). "Collectively, m6A RNA methylation regulators KIAA1429, METTL16, METTL3, IGF2BP2, and YTHDF, and targets NASP, TIMP1, U2AF2, COL18A1, and VEGFA could serve as oncogenes in glioma, while PHLPP2 is a tumor suppressor." (PMID 34589481, 2021). "Our study established and validated a seven-gene signature comprising METTL3, COL18A1, NASP, PHLPP2, TIMP1, U2AF2, and VEGFA, with a good capability for predicting glioma survival, which may guide therapeutic customization and clinical decision-making." (PMID 34589481, 2021).
glioma (continued). "Additionally, we confirmed that PDPN and TIMP1 were higher expressed in high-grade glioma, and the Pearson correlation validated that PDPN and TIMP1 were correlated with marker gene of macrophage and indicated m6A gene." (PMID 33123464, 2020). "We found TIMP1 as one of the proteins which help to distinguish healthy from gliomas, but in our study, its significance for survival was not confirmed." (PMID 31861636, 2019). "We could hypothesize that these genes might contribute to the malignance of glioma and SAA1 and TIMP-1 may be biomarkers in GBM." (PMID 30867991, 2019). "In addition, we found several hub genes with worse OS and higher expression level in glioma patients, including VEGFA, NDC80, TIMP1, SAA1, CENPA, CENPF, and NCAPG and we firstly found relationship of SAA1, TIMP1, and molecular pathology in GBM." (PMID 30867991, 2019). "Furthermore, many proteins associated with tissue remodelling and cellular invasion (e.g. TIMP1, TIMP2) were clearly deregulated in the dataset in a manner suggesting a heightened state of cellular plasticity (e.g. ‘glioma invasiveness signalling’)." (PMID 25800737, 2015). "This might be because invasion is independent of glioma grade, or that TIMP1 as a multipotent protein promotes glioma invasion and migration through different mechanisms." (PMID 37091145, 2023). "Furthermore, highly expressed TIMP1 can be recognized as an independent prognostic biomarker, as the p-value of overall survival (OS) was 0.007 and the p-value of diseasE−free survival (DFS) was less than 0.0001 in glioma patients." (PMID 35778451, 2022). "To further understand the role of APOBEC3G in Smad2 deactivation in gliomas, we determined its role in mediating the expression of the Smad2-targeted genes Thrombospondin 1 (TSP-1), matrix metallopeptidase 2 (MMP2) and TIMP metallopeptidase inhibitor 1 (TIMP-1)." (PMID 28903341, 2017). "Reverse transcription-PCR (RT-PCR) analyses of total RNA from surgical tumour specimens revealed unique expression patterns for the 4 members of the TIMP family, with TIMP-1 and -4 showing positive and negative correlations, respectively, with glioma malignancy." (PMID 11437402, 2001). "Although the expression of IGFBP2 is controlled by epigenetic DNA methylation in glioma patients 42, we find no significant different methylation intensity of IGFBP2 and TIMP1 genes between old and young LGG patients." (PMID 32328202, 2020).
Hypertension (57 papers, 2008 to 2025). The presence of chronic increased pressure in the systemic arterial system. "In conclusion, our study evaluated the ability of HLA-B and TIMP1 to participate in ventricular remodeling caused by hypertension." (PMID 38728374, 2024). "In the present study, adopting a bioinformatics approach and confirming our findings on a small cohort of hypertensive patients, we found that HLA-B and TIMP1 genes are associated with hypertension-related ventricular remodeling." (PMID 38728374, 2024). "An increase in Timp1 level was found to be associated with hypertension and left ventricular diastolic dysfunction." (PMID 37872946, 2023). "We reported for the first time that circulating levels of TIMP-1 at admission are associated with hematoma volume independently of hypertension, NIHSS and hematoma location in two independent cohorts of ICH patients." (PMID 32587306, 2020). "Elevated levels of MMP-9 and TIMP-1 in patients with essential hypertension are associated with increased arterial stiffness." (PMID 33419373, 2020). "In contrast, some studies have reported that increased TIMP-1 levels were associatedwith an increased incidence of hypertension and risk of BP progression." (PMID 26039662, 2015). "Although in the younger male group, TIMP1 rs4898 variant was associated with hypertension risk and MMP9 rs3787268 variant had a borderline protection from DM risk, none of them were associated with SDICH risks in the young males." (PMID 25932641, 2015). "AngII hypertension was associated with significant increases in aortic wall to lumen ratio (∼29%), collagen deposition (∼14%) and expression of TIMP1 and TIMP2." (PMID 24205262, 2013). "In particular, we clearly demonstrated that lower serum TIMP-1 is the most powerful independent factor associated with higher AF incidence in patients with essential hypertension and normal left ventricular systolic function." (PMID 22204652, 2011). "We found that TIMP-1 concentration was positively associated with hypertension." (PMID 39917664, 2024). "Moreover, genetic polymorphism of TIMP-1 has been linked with higher risk of developing certain diseases such as essential hypertension or intracerebral hemorrhage, which share certain risk factors with preeclampsia." (PMID 35885543, 2022). "This hypertension-associated increase in TIMP-1 may contribute to an altered MMP-1/TIMP-1 ratio that already favors ECM increase over degradation." (PMID 32039229, 2019). "In the younger male group (<65 y/o), we found that TIMP1 rs4898 minor allele was associated with hypertension risk (OR = 2.16, 95% CI 1.24 to 3.76, P = 0.006) and MMP9 rs3787268 minor allele had a borderline protection from DM risk (OR = 0.5, 95% CI 0.26 to 0.98, P = 0.04)." (PMID 25932641, 2015). "Accordingly, TIMP1 knockout mice showed reduced fibrosis in a model of hypertension-induced chronic cardiac injury." (PMID 39970910, 2025). "According to a study investigating TIMP-1 as a marker of left ventricular diastolic dysfunction and fibrosis in hypertension, patients with hypertension exhibited higher levels of TIMP-1, CITP, and PICP compared to healthy individuals." (PMID 40291288, 2025). "The expression of TIMP1 is up-regulated in patients with hypertension-related myocardial fibrosis and ventricular remodeling." (PMID 38728374, 2024). "Initially, individuals with hypertension exhibit increased levels of tissue inhibitor of metalloproteinase-1 (TIMP-1), a key regulator of ECM structure." (PMID 39114830, 2024). "Eucalyptol significantly decreased the increased plasma levels of MMP-9 and TIMP-1 in chronic nicotine-induced hypertension inrats and its combination with lisinopril exerted more significant effects compared to each drug alone." (PMID 37886137, 2023). "Patients with hypertension, left ventricular hypertrophy, or impaired left ventricular systolic function had higher serum TIMP-1 levels compared to their healthy counterparts." (PMID 38162139, 2023).
Hypertension (continued). "In conclusion, eucalyptolsignificantly decreased the increased plasma levels of MMP-9 and TIMP-1 in nicotine-induced hypertension in rats." (PMID 37886137, 2023). "Four TIMPs have been described in vertebrates, namely TIMP-1, −2, −3 and −4, and important roles of those molecules in hypertension and PE have been suggested." (PMID 37538930, 2022). "TIMP-1 and MMP-1 are associated with hypertensive remodeling and correlate with extent of target organ damage (TOD) in patients with hypertension." (PMID 33419373, 2020). "It was therefore suggested, that both Timp1 and Mmp2 were potential plasma biomarkers of cardiovascular remodeling in response to hypertension." (PMID 28880918, 2017). "The levels of TIMP-1 in the hypertensive disorders in pregnancy and control groups exhibited positive correlations with the MMP-1 levels in the placenta (r=0.891, P<0.05) and the decidua (r=0.914, P<0.05)." (PMID 25667666, 2015). "In a hypertension animal model, angiotensin II increased TIMP-1 mRNA level in both Nox1 deficient mice and wild type mice but increased TIMP-1 mRNA protein levels much more tremendously in Nox1 deficient mice than wild type mice." (PMID 24669283, 2014). "Collectively, these data support the idea that proteasome activity contributes to AngII-induced hypertension and hypertensive aortic vascular remodeling at least in part by modulating TIMP1/2 and MMP2 function." (PMID 24205262, 2013). "TIMP-1 plays a role in hypertension, LV hypertrophy, atherosclerosis, and coronary plaque rupture." (PMID 40095713, 2025). "Effects of eucalyptol, a key component of eucalyptus globules, on matrix metalloproteinase-9 (MMP-9) and its tissue inhibitor(TIMP-1), compared with lisinopril, were investigated in a model of hypertension induced by chronic intraperitoneal (IP) injection oflow dose nicotine in rats." (PMID 37886137, 2023). "Moreover, following management of the cardiovascularrisk, MMP-9 levels decreased and TIMP-1 levels increased suggesting a potential role for these markers in hypertension." (PMID 37886137, 2023). "Therefore, it is of interest to evaluate effects of eucalyptol, compared to lisinopril,on systolic blood pressure and plasma levels of MMP-9 and TIMP-1 in a rat model of hypertension induced by chronic exposure tonicotine." (PMID 37886137, 2023). "TIMP-1 is a major endogenous inhibitor of MMP-9 that may affect the responsiveness of hypertensive disorders of pregnancy to therapy." (PMID 33419373, 2020). "In addition, significantly higher TIMP-1 levels have been reported in hypertensiveindividuals as compared with normotensive individuals; however, TIMP-1 levels are notelevated in hypertension alone, but only in patients with diastolic dysfunction andfibrosis." (PMID 26039662, 2015). "In patients with hypertension, there is a marked increase in serum TIMP-1 level." (PMID 25861361, 2015). "It is speculated that MMP-1 and TIMP-1 may be involved in the occurrence and development of hypertension disorders in pregnancy in every part of the maternal-fetal interface." (PMID 25667666, 2015). "Moreover, diastolic dysfunction was highly probable in individuals whose TIMP-1 levels exceeded a certain threshold, indicating that TIMP-1 may serve as a reliable noninvasive marker of myocardial fibrosis in hypertension." (PMID 40291288, 2025). "In addition to clinical studies showing that TIMP1 is involved in the occurrence and development of myocardial fibrosis, there have also been animal experiments showing the molecular mechanism of how elevated TIMP1 promotes hypertensive myocardial fibrosis." (PMID 38728374, 2024). "The MMP-9/TIMP-1 ratio (an index of net MMP-9 activity) is associated with great arterial stiffness, as assessed by carotid-femoral pulse wave velocity, but not with muscular arterial elasticity, as assessed by carotid-radial pulse wave velocity (CRPWV), in patients with hypertension." (PMID 33923477, 2021).
Hypertension (continued). "This suggests an interplay between these factors that may be mediated by an altered MMP-1/TIMP-1 ratio that favors ECM deposition, and hypertension-associated tissue hypoxia that increases HIF-1 expression that influences the development of aberrant keloid fibroblasts and myofibroblasts." (PMID 32039229, 2019). "Variable inflammation, which could include a combination of systemic conditions like heart disease, high blood pressure, bowel disease, and muscle and joint diseases, was associated with increased concentrations of IL-8, MMP-8, MMP-8/TIMP-1 ratio, lysozyme and total protein." (PMID 23637817, 2013). "This makes this combination particularlyuseful in hypertension and related cardiovascular disorders where suppression of MMP-9 and TIMP-1 activities decreases the relatedcomplications and improves the overall morbidity and mortality." (PMID 37886137, 2023). "Timp1, one of the markers of ECM remodeling in the cardiovascular system, is involved in the development of hypertension-mediated damage of the main target organs." (PMID 37872946, 2023). "Individuals with T2DM in combination with arterial hypertension exhibit maximum TIMP-1 levels and TIMP-1:MMP-2 and TIMP-1:MMP-9 ratios, as well as enhanced secretion of tumor necrosis factor alpha (TNF-α), interleukin-16 (IL-6), and IL-17." (PMID 33419373, 2020). "Patients with hypertension treated with the ACE inhibitor lisinopril, demonstrate an increase in MMP, a decrease in TIMP-1 levels, and increased extracellular collagen maturation." (PMID 32039229, 2019). "Thus, alterations in plasma MMP-9 and TIMP-1 levels are related to a pathological remodeling of target organs as heart, vessels, or kidney during the development of diabetic nephropathy, albuminuria, arterial stiffness, or hypertension, among other pathological situations." (PMID 28791014, 2017). "Collectively, these data support the idea that the proteasome is critically involved in controlling the balance of TIMP1/TIMP2 expression and MMP2 activity which in turn modulates aortic extracellular matrix turnover in hypertension." (PMID 24205262, 2013). "Patients reporting high blood pressure presented with higher concentrations of MMP-8 and lysozyme, as well as an increased MMP-8/TIMP-1 ratio but these differences were lost after compensation for age, gender and smoking habits." (PMID 23637817, 2013). "MMP-8 concentration was lower and TIMP-1 higher in individuals with hypertension and in those with antihypertensive medication when compared to individuals with no measured hypertension and no antihypertensive medication (p < 0.001 for both proteins)." (PMID 39917664, 2024). "This combination could beuseful in hypertension and related cardiovascular disorders because suppression of MMP-9 and TIMP-1 activities will decrease thecomplications and improves the overall morbidity and mortality." (PMID 37886137, 2023). "The absence of systemic changes in Timp1 levels suggested that the onsets of hypertension-induced senescence were not synchronized among organs." (PMID 37872946, 2023). "Subgroup analysis revealed that female sex, age < 65 years, hypertension (HTN), body mass index (BMI) ≥ 24 kg/m2, CHA2DS2-VASc score < 2, HAS-BLED score < 3, and EHRA score = 3 combined with high TIMP-1 level would perform well at predicting AF recurrence after RFCA." (PMID 36312240, 2022). "Furthermore, our results showing the correlations between MMP-3, -9, their ratios with TIMP-1 and blood pressure as well as endothelial-dependent response could be beneficial for the prevention of obesity-related cardiovascular diseases such as hypertension or atherosclerosis." (PMID 34625635, 2021). "Higher concentrations of TIMP-1, an inhibitor of MMP-1 seen in hypertension and keloid fibroblasts, may reduce turnover of type 1 collagen, which is present at higher levels in KLs." (PMID 32039229, 2019).
Hypertension (continued). "Zile and coworkers confirmed that in patients with hypertension with or without diastolic heart failure, circulating TIMP-1 levels, but not metalloproteinases, were elevated compared to normotensive controls." (PMID 27959898, 2016). "Subgroup analyses showed that the relationship between TIMP‐1 and cognitive impairment was similar across subgroups stratified according to age, sex, body mass index, admission NIHSS score, smoking status, alcohol consumption, history of hypertension and receiving immediate BP reduction." (PMID 32431079, 2020). "In the last years, MMP-1 and TIMP-1 (the inhibitor of soluble MMPs but not of MT-MMP), have been one of the most studied for hypertension-mediated damage to vessels and target organs." (PMID 35324807, 2022). "In our recent study, age, gender and pre-existing hypertension did not influence the plasma levels of MMP-9 and TIMP-1 at any time point." (PMID 30157791, 2018).